SERINC4 (serine incorporator 4)
Description:
Incorporates a polar amino acid serine into membranes and facilitates the synthesis of two serine-derived lipids, phosphatidylserine and sphingolipids.
Synonyms: FLJ40363
Tractability: Antibody: UniProt predicts a signal peptide or a membrane-spanning region.
Gene: Protein-coding gene on chromosome 15 (43,794,162 to 43,800,220, reverse strand). Ensembl gene ENSG00000184716.
Subcellular location: Membrane
Pathways (Reactome):
Metabolism: Serine metabolism
Gene Ontology:
Cellular component: membrane
Genetic constraint (gnomAD): Loss-of-function variants: 48 observed, 46.76 expected, observed/expected ratio (o/e) 1.03, 90% interval 0.81 to 1.31. The upper end of that interval is the gene's LOEUF score, 1.31, which puts it in group 5 of 6, group 1 being the genes least tolerant of losing a copy. Missense variants: 715 observed, 641.47 expected, observed/expected ratio (o/e) 1.11, 90% interval 1.05 to 1.19. Synonymous variants: 264 observed, 252.07 expected, observed/expected ratio (o/e) 1.05, 90% interval 0.95 to 1.16.
Homologues: Orthologues: chimpanzee SERINC4 (99% identical), pig SERINC4 (86% identical), dog SERINC4 (84% identical), rat Serinc4 (80% identical), mouse Serinc4 (78% identical), rabbit SERINC4 (51% identical), tropical clawed frog serinc4 (51% identical), zebrafish serinc4 (50% identical), Drosophila melanogaster Serinc (28% identical), Caenorhabditis elegans R11H6.2 (27% identical), Caenorhabditis elegans Y57E12AL.1 (26% identical). Paralogues in human: SERINC5 (36% identical), SERINC1 (31% identical), SERINC2 (31% identical), SERINC3 (29% identical).